CELF2 (CUGBP Elav-like family member 2)
Diseases named in the same sentence as CELF2 in open-access papers (continued):
Sharing a sentence is not in itself a finding about the gene and the disease.
CELF2 also shares sentences with these, for which no sentence is quoted: non-small cell lung carcinoma (3 papers); cervical cancer (2); colon (2); infection (2); melanoma (2); nasopharyngeal carcinoma (2); prostate carcinoma (2); acute leukemia (1); acute lymphoblastic leukemia (1); allergic rhinitis (1); autism (1); bladder urothelial carcinoma (1); blood cancer (1); calculus (1); colon adenocarcinoma (1); erectile dysfunction (1); esophageal carcinoma (1); head and neck squamous cell carcinoma (1); invasive breast carcinoma (1); kidney chromophobe (1); liver cancer (1); low grade glioma (1); lung adenocarcinoma (1); multiple myeloma (1); Nematode Infection (1); neurological disease (1); pancreatic adenocarcinoma (1); prostate adenocarcinoma (1); rectal cancer (1); rectum adenocarcinoma (1).
A further 6 diseases each share a sentence with CELF2 in 1 paper.